HAPLN1 (hyaluronan and proteoglycan link protein 1)
Diseases named in the same sentence as HAPLN1 in open-access papers (continued):
Sharing a sentence is not in itself a finding about the gene and the disease.
tumor (continued). "On the other hand treatment with recombinant HAPLN-1 increases the T cell recruitment and reduces the tumor growth." (PMID 31134198, 2019). "Taken together, these findings indicate that HAPLN1 emerges in mesenchymal-committed tumor progenitor cells driving tumor aggressiveness and poor outcome in HCC." (PMID 27191501, 2016). "HAPLN1 mRNA levels were measured by real-time PCR in 82 HCCs from 70 patients, 5 histologically normal liver controls, 11 FNHs and 66 matching non-tumor liver samples." (PMID 27191501, 2016). "HAPLN1 and the tumor progenitor cell markers CD44 and LGR5 were detected in tumor cells at the tumor-stroma interface and in cells arranged in an “Indian file” pattern." (PMID 27191501, 2016). "In addition to the tumor-up expressed protein, we identified tumor-down expressed proteins such as HAPLN1." (PMID 39305996, 2024). "Indeed, we observed that HAPLN1 protein expression in tumors of PDAC patients was localized in tumor cell areas." (PMID 37095087, 2023). "Next, we sought out to understand which cells within the tumor were producing HAPLN1." (PMID 37095087, 2023). "In addition, CAFs are also closely related to tumor invasion and progression, such as the Hyaluronan and proteoglycan link protein 1 (HAPLN1) derived from CAFs can promote tumor invasion." (PMID 37666813, 2023). "Levels of TYMS-AAb, IGFBP5-AAb, and HAPLN1-AAb all declined after tumor resection." (PMID 36139323, 2022). "Compared with the presurgical levels, serum levels of TYMS-AAb, IGFBP5-AAb, and HAPLN1-AAb decrease at 3 months after surgery and remain low up to one year, implying a possibility of utilizing CMT-associated AAbs for predicting tumor recurrence or treatment responses." (PMID 36139323, 2022). "We also confirmed the HAPLN1 levels in isolated tumour tissues from different groups." (PMID 34724589, 2022). "These inconsistent effects of HAPLN1 on the prognosis of patients with different tumours suggested that roles of fibroblasts or HAPLN1 might be tissue-dependent." (PMID 34724589, 2022). "Overexpression of HAPLN1 is correlated with tumor progression of mesothelioma." (PMID 36139323, 2022). "Importantly, SHG assays with mouse xenograft models and human samples further demonstrated CAFs-derived HAPLN1 increased tumour invasiveness through ECM remodeling." (PMID 34724589, 2022). "HAPLN1 also mediates E-cadherin to regulate tumor cell attachment in CRC." (PMID 34966673, 2021). "This suggests that the extracellular HAPLN1 may be involved in developing resistance and suppress the anti-tumour effect of BTZ28." (PMID 33972578, 2021). "We also show that HAPLN1 correlated with collagen in CRC, indicating that HAPLN1 may regulate collagen in the tumor microenvironment." (PMID 34966673, 2021). "We hypothesized that HAPLN1 is a key ECM protein that regulates tumor growth and development in CRC." (PMID 34966673, 2021). "However, overexpression of HAPLN1 in CRC cells increased E-cadherin proteins after TGF-β stimulation, indicating that HAPLN1 regulates E-cadherin and reduces tumor cell growth." (PMID 34966673, 2021). "We hypothesize that HAPLN1 can be hijacked by tumor evolution as a selective advantage for cancer progression." (PMID 27191501, 2016). "Interestingly, we discovered that two of the most highly expressed ACC target genes, VCAN and HAPLN1, can bind within a predicted ECM complex in ACC tumor cells and, in the case of HAPLN1, appear to be regulated by RUNX1 activation." (PMID 25587024, 2014). "Taken together, we could demonstrate that HAPLN1 expression in tumor cells modulates TNFα signaling to promote a highly plastic phenotype that facilitates invasion and colonization of the peritoneum, among others by creation of a pro-tumoral immune microenvironment." (PMID 37095087, 2023).
tumor (continued). "Interestingly, some of these features could be mimicked by stimulating with TNFα and inhibition of TNFα reverted the effects of HAPLN1, indicating that TNFα is responsible for the tumor cell plasticity observed in the presence of HAPLN1." (PMID 37095087, 2023). "ITIHs, LYVE-1, RHAMM, HAPLN1, and PHBP levels are elevated in certain tumour types, while decreased expression of these HAIMs has been evident in other malignancies." (PMID 38791985, 2024). "We previously reported that hyaluronan and proteoglycan link protein 1 (HAPLN1) produced by stromal cells induces activation of NF-κB, a tumor-supportive transcription factor, and promotes drug resistance in MM cells." (PMID 36625202, 2023). "The data presented so far indicate that HAPLN1 expression in PDAC cells induces a more aggressive, highly plastic state and a more tumor-permissive niche within the peritoneal cavity." (PMID 37095087, 2023). "Since HAPLN1 modified the composition of the ECM, we evaluated how a heterogenous tumor cell population would affect the tumor." (PMID 37095087, 2023). "The CAF-derived hyaluronan and proteoglycan link protein 1 (HAPLN1) promotes ECM remodeling by decreasing the density and size of fibers, as well as increasing the fiber alignment, resulting in tumor invasion and aggression in GC." (PMID 35967313, 2022). "Hyaluronan and proteoglycan link protein 1 (HAPLN1) is a component of the extracellular matrix proteins and promotes tumor invasion through the extracellular matrix remodeling." (PMID 35954313, 2022). "Transfection of HAPLN1 overexpression plasmids into these cells increased protein levels but reduced COL1A1 protein, tumor growth, and cancer cell migration." (PMID 34966673, 2021). "In our study, we observed a decreased gene expression of HAPLN1 in CRC patients compared with healthy controls and normal tissue adjacent to the tumor." (PMID 34966673, 2021). "We also assayed for the main cell components of tumor microenvironment with IHC staining in these zPDXs, including CEA or CA199 for cancer cells and HAPLN1 for stromal cells." (PMID 34164399, 2021). "We found that the mRNA expression of HAPLN1 was decreased in tumors from CRC patients compared with healthy controls and normal tissue adjacent to the tumor using two existing microarray datasets." (PMID 34966673, 2021). "HAPLN1 overexpression restored protein levels in human CRC cells after TGF-β challenge and reduced collagen and tumor cell growth in CRC." (PMID 34966673, 2021). "HAPLN1 is an ECM protein that contributes to cell proliferation, cell–cell interactions, and tumor development." (PMID 34966673, 2021). "Hyaluronan and proteoglycan link protein-1 (HAPLN1) is a component of the extracellular matrix (ECM) proteins and involved in the tumor environment in the colon." (PMID 34966673, 2021). "HCCs with microscopic vascular invasion had high mRNA levels of HAPLN1, LGR5, LEF1, SOX9, CD44, Glypican 3 and larger tumor size." (PMID 27191501, 2016). "After normalization to anti-BSA levels, standardized ratios of anti-AGR2, anti-HAPLN1, anti-IGFBP5, and anti-TYMS were significantly higher in malignant and early-stage CMTs, suggesting selective amplification of tumor-specific immune responses despite global immune suppression." (PMID 41562247, 2026). "Apart from HAPLN1, clinical data analysis showed that HAPLN3 overexpression was related to breast cancer metastasis and its level was closely related to the depth of tumour invasion, lymph node invasion and distant metastases in ccRCC." (PMID 38791985, 2024).
tumor (continued). "The reasons to investigate HAPLN1 functions were based on the finding that HAPLN1 was one of the most upregulated HA-related genes in PDAC patients and on the fact that HA is a critical component of the tumor microenvironment, modifying EMT and invasion capacity of cancer cells." (PMID 37095087, 2023). "Further, our data indicate that tumor cells with high HAPLN1 expression become more independent of CAFs as matrix producers." (PMID 37095087, 2023). "To confirm that the decrease of HAPLN1 mRNA translates to reduced protein levels in CRC patients, we assessed the HAPLN1 protein in tumor and normal tissues adjacent to tumor tissues from 59 CRC patients using immunohistochemistry, and the HAPLN1 protein was mainly produced by CRC epithelial cells." (PMID 34966673, 2021). "However, although HAPLN1 does not lower the CD8: Treg ratio, HAPLN1 may alter the capability of neutrophils and polymorphonuclear myeloid-derived suppressor cells (PMN-MDSCs) to reach the tumour site." (PMID 35884596, 2022).
cancer (20 papers, 2006 to 2025). A tumor composed of atypical neoplastic, often pleomorphic cells that invade other tissues. "Our work provides new mechanistic insight into how MM cells use a previously undescribed receptor complex to co-opt a matrikine derived from the structural ECM protein HAPLN1 as a cancer-promoting signaling element." (PMID 36625202, 2023). "Our retrospective study revealed HAPLN1 mRNA level was higher in the moderately (Grade 2) (P < 0.01) or poorly (Grade 3) (P < 0.05) differentiated cancers than that in the well differentiated cancers (Grade 1) detected by qPCR." (PMID 34724589, 2022). "Limited information is known about the clinical relevance of HAPLN1 with the disease progressions, including cancer." (PMID 34724589, 2022). "In conclusion, HAPLN1 accelerates proliferation and reduces apoptosis of RA-FLSs to form a pathological pannus, mimicking the aggressive feature of cancer cells." (PMID 35720292, 2022). "High levels of HAPLN1 mRNA were detected in the cancer tissues compared with the normal stomach tissues (P = 0.000041)." (PMID 34724589, 2022). "Cartilage link protein HAPLN1 is being studied as a candidate biomarker, found to be overexpressed in mesothelioma stage 1 along with a highly expressed cancer biomarker osteopontin (OPN1) located in the same gene set." (PMID 23516416, 2013). "The imprint conditions were optimized for potentiometry using BSA (66 kDa) protein, due to its similarity in size with HAPLN1 cancer biomarker (65 kDa)." (PMID 23516416, 2013). "We selected BSA protein (65 kDa) for optimization process due to its similar size to cancer biomarker candidate HAPLN1." (PMID 23516416, 2013). "Extracellular HAPLN1 modifies cancer cells and fibroblasts, rendering them more immunomodulatory." (PMID 37095087, 2023). "Furthermore, HAPLN1 expression was up-regulated in cancer tissues compared with normal stomach tissues (P < 0.01)." (PMID 34724589, 2022). "HAPLN1 overexpression restored HAPLN1 protein and reduced cancer cell growth." (PMID 34966673, 2021). "We have shown that HAPLN1 overexpression in cancer cells restored p-Smad2/3 to control levels, indicating that HAPLN1 may regulate the TGF-β signaling pathway." (PMID 34966673, 2021). "This leads to a decrease of collagen in the cancer cells, indicating that HAPLN1 may regulate collagen formation in CRC." (PMID 34966673, 2021). "HAPLN1 was second highest expressed gene in LECs and as tumors take the advantage of these metastatic potential enhancing molecules, the observed high HAPLN1 expression can lead to new therapeutic treatments for metastasis of cancer to lymph nodes." (PMID 23516416, 2013). "This opposing interaction between cancer cells and CAF-derived HAPLN1 in different cancers may indicate the significance of the composition of all CAF secretomes for the invasion of cancer cells since other factors secreted by CAFs may determine in which direction the HAPLN will act." (PMID 38562556, 2024). "However, the exact mechanism through which HAPLN1 engenders a pro-inflammatory TME, or why its high expression is associated with poor OS of patients with different cancer types remains unclear." (PMID 36625202, 2023). "We define HAPLN1 as a mediator of peritoneal dissemination in PDAC, by inducing a highly plastic phenotype in cancer cells, which leads to a pro-tumoral metastatic niche." (PMID 37095087, 2023). "Hyaluronan and proteoglycan link protein-1 (HAPLN1) is a HA and chondroitin sulfate proteoglycan (CSPG) crosslinker in the ECM, with so far poorly understood roles in cancer." (PMID 37095087, 2023). "scRNA-seq further corroborated that HAPLN1-expressing cells are largely fibroblasts of normal origin; a phenotype conspicuously absent in cancer tissues." (PMID 39305996, 2024).
cancer (continued). "We further showed in MM cancer cells that the PTR1 domain of HAPLN1 (HAPLN1-PTR1), but not full-length protein, activated the transcription factor NF-κB, a mediator of inflammation and cell survival that has been implicated in cancer progression." (PMID 36625202, 2023). "In addition, when stimulating bone marrow-derived macrophages (BMDMs) with cancer cell conditioned medium, we detected significantly higher levels of the anti-inflammatory macrophage marker Arg1 when KPC cells expressed HAPLN1, indicating that HAPLN1 in ECM promotes TAM education." (PMID 37095087, 2023). "It is therefore of great interest to examine the potential role of overexpressed HAPLN1 as a matrikine, rather than an ECM structural element, in other cancer types and whether these malignancies also employ a CH60/TLR4 complex to detect a HAPLN1 matrikine to promote pro-tumorigenic properties." (PMID 36625202, 2023).
infection (1 paper, 2023). The state of being infected such as from the introduction of a foreign agent such as serum, vaccine, antigenic substance or organism. "Some of the highly expressed genes (Log2 FC > 3.5) in inverse manner during Neisseria and Borrelia like HAPLN1, MT3, PITX2, ID4, ELAFIN, SLPI, etc., could be targeted to know their relevance in favoring or resisting the infection." (PMID 38179419, 2023).
skeletal diseases (1 paper, 2014). "Combined with known skeletal defects associated with the loss of Hapln1 in the mouse, and with skeletal diseases associated with Hapln1 polymorphisms in human, these findings demonstrate that the role of Hapln1a is conserved in zebrafish." (PMID 24533114, 2014).
HAPLN1 also shares sentences with these, for which no sentence is quoted: musculoskeletal diseases (3 papers); lung carcinoma (2); Arthritis (1); atherosclerosis (1); atrial fibrillation (1); dependence (1); depression (1); dissection (1); Ehlers-Danlos syndrome (1); heart failure (1); Hyperreflexia (1); juvenile idiopathic arthritis (1); lymph node metastasis (1); memory impairment (1); Non-alcoholic fatty liver disease (1); Obesity (1); osteosarcoma (1); prostate carcinoma (1); renal cell carcinoma (1); spinal cord injury (1); staphylococcus aureus infection (1); Stroke (1); thyroid carcinoma (1); triple-negative breast carcinoma (1); tuberculosis (1).